HOTTIP (HOXA distal transcript antisense RNA)
Diseases named in the same sentence as HOTTIP in open-access papers (continued):
Sharing a sentence is not in itself a finding about the gene and the disease.
glioma (continued). "Moreover, ectopic expression of HOTTIP inhibited cell proliferation and decreased the number of S-phase cells in human glioma cell lines, and over-expression of HOTTIP promoted apoptosis in human glioma cell lines." (PMID 27733185, 2016). "In this study, we evaluated the expression of HOTTIP in glioma tissues." (PMID 27733185, 2016). "Taken together, these findings suggested that high levels of HOTTIP reduced glioma cell growth." (PMID 27733185, 2016). "To understand the molecular mechanism by which HOTTIP suppresses glioma cell growth, we detected the expression of 370 different key genes involved in the apoptosis of U87-MG cells over-expressing pcDNA-HOTTIP or empty vector using the Apoptosis PCR 384HT Array." (PMID 27733185, 2016). "In addition, the expression of HOXA10 and HOXA13 increased in the WHO IV gliomas compared to the WHO II & III gliomas, and the mRNA expression of HOTTIP increased from WHO II gliomas to WHO IV gliomas." (PMID 26356815, 2015). "In addition, high-grade gliomas had high transcriptional levels of HOTTIP, which is a lncRNA that is situated at the 5′ end of the HOXA locus, but this difference was not statistically significant." (PMID 26356815, 2015). "Similarly, hypoxia-induced upregulation of HOTTIP can promote metastasis in gliomas." (PMID 40004471, 2025). "However, little is known regarding how HOTTIP regulates glioma development." (PMID 27733185, 2016). "HOTTIP may act as a tumour suppressor in glioma cells in vitro and in vivo." (PMID 27733185, 2016). "Thus, this evidences suggests that HOXA13 knockdown may cause G0/G1 arrest by inhibiting SMAD2/SMAD3 pathway and this process could be regulated by HOTTIP in glioma." (PMID 26356815, 2015). "In summary, these observations increased our confidence in the finding that HOTTIP increases miR-10b and over expression of both leads to EMT in glioma cells." (PMID 35402278, 2022). "However, little is known about whether and how HOTTIP regulates glioma development." (PMID 27733185, 2016). "In the present study, we first analyzed the expression of HOXA9, HOXA10, HOXA11, and HOXA13 protein in glioma tissues; we then further analyzed the expression of HOXA9, HOXA10, HOXA11, HOXA13, and HOTTIP mRNA in the same samples." (PMID 26356815, 2015). "Further, HOTTIP facilitated the EMT process in TMZ-resistant A172 and LN229 cells by decreasing E-cadherin expression and increasing Zeb1/Zeb2 (mesenchymal markers) via upregulating miR-10b, resulting in the enhancement of TMZ resistance in glioma." (PMID 36059609, 2022). "However, in the present study, we suggested HOTTIP act as a tumor suppressor in HNSCC, playing a similar role as it does in glioma." (PMID 35210436, 2022). "HOTTIP was identified based on lncRNA array analysis between U87 glioma cells with and without hypoxia." (PMID 35402278, 2022). "In addition to the one report on a connection between HOTTIP and EMT in glioma, there are a few other reports connecting HOTTIP with EMT in some other cancers." (PMID 35402278, 2022). "For example, HOTTIP is upregulated by HIF-1α via binding to the HREs in HOTTIP’s promoter region, increasing the epithelial-mesenchymal transition (EMT) and metastasis of glioma by the miR-101/ZEB1 axis." (PMID 35915091, 2022).
glioma (continued). "In this study, we showed that over-expression of HOTTIP can inhibit the expression of CDK2 and cyclin A proteins and that over-expression of BRE can enhance the expression of CDK2 and cyclin A proteins in the U87-MG and U118-MG glioma cell lines." (PMID 27733185, 2016). "Nevertheless, the function of BRE in relation to the HOTTIP gene in glioma cells has not been investigated." (PMID 27733185, 2016). "Interestingly, another study showed that HOTTIP was overexpressed under hypoxic conditions, and HOTTIP expression in metastatic glioma samples was higher than in glioma samples without metastasis." (PMID 34316694, 2021). "Interestingly, another study showed that under hypoxic conditions there is an overexpression of HOTTIP RNA, and the HOTTIP expression in glioma samples with metastasis was approximately 4 folds higher than in glioma samples without metastasis." (PMID 30583549, 2018). "To investigate the role of HOTTIP in glioma progression, we first established stable over-expression of HOTTIP in the U87-MG and U118-MG cell lines, and CCK-8 assays showed that over-expression of HOTTIP decreased cell proliferation compared with the control group in both cell lines." (PMID 27733185, 2016). "Moreover, several of them (e.g., HOXA1, A5, A6, A7, A10, D9, and D10) were expressed in most IDHwt glioma samples, constituting thus the core HOX signature in IDHwt samples, whereas HOXB1, HOXC12, HOTTIP, and HOXB‐AS4 were not reactivated." (PMID 33720519, 2021).
breast cancer (17 papers, 2017 to 2025). A primary or metastatic malignant neoplasm involving the breast. "The results of this study provide important light on the association between HOTTIP expression and clinical and biological characteristics in breast cancer patients." (PMID 38186456, 2023). "Previous research has linked HOTTIP to the development and spread of tumors in a number of malignancies, including breast cancer." (PMID 38186456, 2023). "According to current literature, the high expression of HOTTIP in tumor cells is associated with poor prognosis and promotes the stemness of breast cancer stem cells." (PMID 38186456, 2023). "The diagnostic utility of circulating HOTTIP levels in breast cancer has been examined in a few studies." (PMID 38186456, 2023). "We also verified that HOTTIP was associated with poor outcome in breast cancer patients using Kaplan‐Meier analysis." (PMID 32307830, 2020). "Our results demonstrate a pivotal role of HOTTIP in breast cancer pathogenesis by applying loss-of-function experiments in vitro and in vivo." (PMID 29415429, 2018). "Here, we report lncRNA HOTTIP, which is specifically amplified in a breast cancer cell line and is associated with breast cancer cell growth, cell cycle arrest, apoptosis, and migration, probably by partly mediating HOXA11 expression." (PMID 29415429, 2018). "It was also found an indication that high HOTTIP expression was associated with worse survival in breast cancer patients by microarray analysis (GSE20711, GSE16446 and GSE9195)." (PMID 28036281, 2017). "In addition to its potential as a diagnostic biomarker, HOTTIP has also been investigated as a breast cancer prognostic biomarker." (PMID 38186456, 2023). "Furthermore, lower overall survival and disease-free survival rates in breast cancer patients have been often associated to a higher HOTTIP expression." (PMID 38186456, 2023). "In addition, a growing body of research indicates that dysregulated HOTTIP expression is linked to the onset and progression of disease, particularly breast cancer." (PMID 38186456, 2023). "Breast cancer is one among the cancers that have been linked to HOTTIP dysregulation." (PMID 38186456, 2023). "Although HOTTIP has been reported to be one of the predictors of breast cancer prognosis, the underlying role of HOTTIP in the pathogenesis of breast cancer still remains unknown." (PMID 29415429, 2018). "Finally, association between HOTTIP levels and clinicopathological factors and prognosis was also analyzed in an independent validation cohort including 100 breast cancer cases." (PMID 28036281, 2017). "Furthermore, Gene Expression Omnibus was performed to evaluate the association of HOTTIP expression with the prognosis in breast cancer patients." (PMID 28036281, 2017). "However, the biological function and underlying modulatory mechanism of HOTTIP in breast cancer stem cells (BCSCs) remains unknown." (PMID 32307830, 2020). "The results of the study confirmed a positive relation of HOTTIP expression and breast cancer aggressiveness and metastatic behavior." (PMID 38186456, 2023). "This makes HOTTIP an attractive molecule to research for its possible application in the detection and treatment of breast cancer." (PMID 38186456, 2023). "The fundamental processes through which HOTTIP promotes the development of breast cancer are currently being studied." (PMID 38186456, 2023). "We will talk about the dysregulation of HOTTIP in breast cancer, the current knowledge of its molecular roles, and its potential as a non-invasive diagnostic and prognostic tool." (PMID 38186456, 2023). "Our findings raise the possibility of HOTTIP serving as a biomarker for aggressive breast cancer characteristics from a clinical standpoint." (PMID 38186456, 2023). "Our research illuminates the complex interactions between HOTTIP expression and clinicopathological traits in breast cancer." (PMID 38186456, 2023).
breast cancer (continued). "Meanwhile, a study also demonstrated that HOTTIP acts as a molecular sponge for miR-148a-3p to increase WNT1 expression, thereby modulating the CSC-like properties of breast cancer, suggesting that HOTTIP is a new target for breast cancer treatment." (PMID 36338699, 2022). "It has been reported that HOTTIP expression is significantly increased in breast cancer tissues, compared to adjacent non‐cancerous tissues." (PMID 32307830, 2020). "In this study, we found that HOTTIP was markedly up‐regulated in BCSCs and had a positive correlation with breast cancer progression." (PMID 32307830, 2020). "Four of the ten closest genes with probes available showed moderate association with breast cancer survival at P < 0.005 (HOXA9, HOTTIP, EVX1 and TAX1BP1), with these associations mainly observed for ER-negative breast cancer." (PMID 30787463, 2019). "By in vitro and in vivo experiments, our study indicated the role of lncRNA HOTTIP in breast cancer pathogenesis and its potential mechanism, by partly mediating its adjacent gene HOXA11." (PMID 29415429, 2018). "Thirdly, HOTTIP was revealed to be involved in breast cancer biology, at least partly, by mediating HOXA11 expression." (PMID 29415429, 2018). "This present study provides the first insight into the effect of HOTTIP in breast cancer cell behavior." (PMID 29415429, 2018). "In the present study, we elucidated the involvement of lncRNA HOTTIP in breast cancer pathogenesis and further uncovered a potential bidirectional regulatory loop between HOTTIP and HOXA11 in this process." (PMID 29415429, 2018). "The effect of HOTTIP in direct relation to breast cancer biology was further examined using an in vivo xenograft model in nude mice." (PMID 29415429, 2018). "Future work will validate HOTTIP as a predictive bio-marker for breast cancer chemo-resistance, invasion, and metastasis." (PMID 29415429, 2018). "The Kaplan-Meier survival curves indicated that breast cancer patients with high HOTTIP expression had worse overall survival (P=0.0139) and disease-free survival (P=0.0003)." (PMID 28036281, 2017). "For another, in vitro and in vivo experiments are needed to be conducted to further validate the biological effects of HOTTIP on breast cancer." (PMID 28036281, 2017). "A study on cell lines confirmed that HOTTIP binds to miR-148a-3p and inhibits mediation of Wnt1 which leads to inactivation of Wnt/β-catenin signaling pathway which in turn facilitates the stemness of breast cancer." (PMID 40616679, 2025). "Furthermore, it is crucial to comprehend the mechanisms through which HOTTIP affects breast cancer biology." (PMID 38186456, 2023). "As we continue to delve into the intricate molecular workings of breast cancer this may highlight the future use of HOTTIP." (PMID 38186456, 2023). "The varied character of breast cancer may be reflected in variation in HOTTIP expression patterns, highlighting the need of taking molecular subtypes into account in future research." (PMID 38186456, 2023). "Despite the lack of statistical significance, the data showed a number of interesting patterns that may offer insights on HOTTIP's possible contribution to the development of breast cancer." (PMID 38186456, 2023). "However, the prevalence and functional significance of HOTTIP in breast cancer still requires more investigation." (PMID 34069089, 2021). "Consistently, depletion of HOTTIP suppressed tumour growth in a humanized model of breast cancer." (PMID 32307830, 2020). "Li et al38 demonstrated that miR‐148a‐3p is dramatically decreased in breast cancer stem cells and could be regulated by HOTTIP to suppress the stemness of breast cancer stem cells." (PMID 33026174, 2020). "Consistent with previous studies, we found that HOTTIP is highly expressed in breast cancer cells." (PMID 32307830, 2020).
breast cancer (continued). "Recent studies have reported that HOTTIP plays critical roles in the progression of several types of human malignancies, such as nasopharyngeal cancer, oral tongue squamous cell carcinoma as well as breast cancer." (PMID 31533774, 2019). "To gain further insight into the regulation of the HOTTIP/HOXA11 gene axis in breast cancer, we knocked down HOXA11 using shRNAs (short hairpin RNA, used for stable gene silencing) and chose shRNA #858 as the effective sequence of HOXA11 for the next experiments." (PMID 29415429, 2018). "Consequently, using a series of in vitro and in vivo experiments, our study suggested that HOTTIP is involved in breast cancer tumorigenesis through positively regulating HOXA11." (PMID 29415429, 2018). "We hypothesized that HOTTIP might regulate the biological behavior of breast cancer via regulating HOXA11." (PMID 29415429, 2018). "To explore whether the same holds true in a breast cancer cell line, we silenced HOTTIP expression through siRNAs in MCF-7 cells." (PMID 29415429, 2018). "Thus, the regulatory impact of HOTTIP on the HOXA locus is preserved also during breast cancer tumorigenesis." (PMID 29415429, 2018). "Secondly, to explore the role of HOTTIP in breast cancer biology, in vitro and in vivo experiments were carried out and it was found that HOTTIP knockdown inhibited breast cancer cell proliferation and migration, as well as resulted in cell blockade in the G2/M phase." (PMID 29415429, 2018). "Together, our combined results suggest that high HOTTIP expression may be serving as an unfavorable prognosis predictor for breast cancer patients." (PMID 28036281, 2017). "Although statistical significance could not be established, the recurring patterns in multifocality, disease stage, tumor size, hormone receptor status, and lymph node involvement point to a positive interaction between HOTTIP and the aggressiveness of breast cancer." (PMID 38186456, 2023). "Moreover, further rescue experiments revealed that HOXA11 overexpression could rescue the impact of HOTTIP knockdown in cell pathogenesis in breast cancer, and cell proliferation, colony formation, migration, and apoptosis rate were included." (PMID 29415429, 2018). "HOTTIP (HOXA transcript at the distal tip), one of the many lncRNAs investigated, has demonstrated potential as a possible biomarker for breast cancer." (PMID 38186456, 2023). "Recent research has focused on the lncRNA HOTTIP (HOXA transcript at the distal tip), which has a function in breast cancer metastasis and carcinogenesis." (PMID 38186456, 2023). "Our study is the first to report that HOTTIP regulates the CSC‐like properties of BCSCs by as a molecular sponge for miR‐148a‐3p to increase WNT1 expression, offering a new target for breast cancer therapy." (PMID 32307830, 2020). "Among the most affected ncRNAs, we found that sorafenib mediated the dysregulation of the lncRNAs GAS5, HOTTIP and HOXA-AS2 and the miR-126-3p, in a panel of human cancer cell lines (HCC, renal and breast carcinomas)." (PMID 31235746, 2019). "Altogether, these results further substantiate the presumptive role of HOTTIP and HOXA11 in breast cancer cell progression and add new information supporting their interdependently regulated expression." (PMID 29415429, 2018). "Firstly, by detecting the expression of HOXA genes, in both breast cancer MCF-7 cell line and normal mammary epithelial MCF-10A cell line, we found that both HOTTIP and HOXA11 were upregulated in MCF-7 cells in comparison with MCF-10A cells." (PMID 29415429, 2018). "In conclusion, using a combination of in vitro and in vivo approaches, our study highlights the molecular axes comprising HOTTIP and HOXA11 as key players in breast cancer progression." (PMID 29415429, 2018). "Therefore, our data suggest that HOTTIP may be a novel potential oncogene in breast cancer." (PMID 29415429, 2018).
breast cancer (continued). "HOTTIP expression was correlated with tumor size (P=0.025), lymph node status (P=0.009) and TNM stage (P=0.0001) in the breast cancer validation cohort." (PMID 28036281, 2017). "HOTTIP, in addition to its regulation of the right proportion between oncogenic and tumor-suppressing lncRNAs, was reported to promote migration, invasiveness, and EMT of breast cancer cells by regulating the Wnt/β-catenin pathway." (PMID 35328609, 2022). "Additionally, we found that the expression of HOTTIP was much higher in MCF7 and T47D breast cancer cells than in MCF‐10A cells." (PMID 32307830, 2020). "Therefore, we used RT-qPCR technology to detect the expression of HOTTIP and its physical proximity to HOX genes in the breast cancer cell line, MCF-7, and the normal human mammary epithelial cell line, MCF-10A." (PMID 29415429, 2018). "Here, we reported a long non-coding RNA (lncRNA), HOTTIP (HOXA transcript at the distal tip), that may play an important role in the pathogenesis of breast cancer." (PMID 29415429, 2018). "A subsequent study showed that HOTTIP increased the expression of pluripotency markers octamer-binding transcription factor 4 (OCT4) and SRY-box transcription factor 2 (SOX2), and, in this way, it facilitated the stemness of breast cancer cells by regulating the miR-148a-3p/Wnt1 pathway." (PMID 35328609, 2022). "Functional studies revealed that overexpression of HOTTIP markedly promoted cell clonogenicity, increased the expression of the stem cell markers, OCT4 and SOX2, and decreased the expression of the differentiation markers, CK14 and CK18, in breast cancer cells." (PMID 32307830, 2020). "The results obtained in the present study indicate that sorafenib mediated the up-regulation of GAS5 and the down-regulation of HOTTIP and HOXA-AS2 in most HCC, renal and breast cancer cells and probably their expression modulation may lead to a less aggressive cancer phenotype of the cells." (PMID 31235746, 2019). "Hence, HOTTIP may mediate, at least partly, HOXA11 expression involved in cell growth, migration, and apoptosis of breast cancer MCF-7 cells." (PMID 29415429, 2018). "Moreover, the mechanism of HOTTIP involved in breast cancer pathogenesis was not deep enough." (PMID 29415429, 2018).